GPR12 (G protein-coupled receptor 12)
Description:
Brain-specific G protein-coupled receptor involved in regulating diverse physiological processes including neurite outgrowth, meiotic arrest, and lipid and carbohydrate metabolism (By similarity). Functions as a receptor with constitutive G(s)-mediated signaling activity that stimulates cyclic AMP (cAMP) production. Also engages the G(i)/G(o) pathway, which counteracts the cAMP increase driven by G(s) activation. Additionally, two lipids sphingosylphosphorylcholine (SPC) and sphingosine-1-phosphate (S1P) may act as endogenous ligand and activate GPR12.
Synonyms: GPCR21; PPP1R84; GPCR12
Tractability: Small molecule: it belongs to a druggable protein family. Antibody: UniProt places it where antibodies can reach, with high confidence; its Gene Ontology location is reachable by antibodies, with high confidence; UniProt predicts a signal peptide or a membrane-spanning region.
Target class: Family A G protein-coupled receptor; Membrane receptor
Gene: Protein-coding gene on chromosome 13 (26,755,200 to 26,760,802, reverse strand). Ensembl gene ENSG00000132975.
Subcellular location: Cell membrane
Gene Ontology:
Molecular function: protein binding; G protein-coupled receptor activity; sphingosine-1-phosphate receptor activity; phosphatidylcholine binding
Biological process: adenylate cyclase-activating G protein-coupled receptor signaling pathway; G protein-coupled receptor signaling pathway; sphingosine-1-phosphate receptor signaling pathway
Cellular component: cytoplasm; plasma membrane; membrane
Genetic constraint (gnomAD): Loss-of-function variants: 7 observed, 19.62 expected, observed/expected ratio (o/e) 0.36, 90% interval 0.2 to 0.67. The upper end of that interval is the gene's LOEUF score, 0.67, which puts it in group 2 of 6, group 1 being the genes least tolerant of losing a copy. Missense variants: 327 observed, 453.87 expected, observed/expected ratio (o/e) 0.72, 90% interval 0.66 to 0.79. Synonymous variants: 201 observed, 198.3 expected, observed/expected ratio (o/e) 1.01, 90% interval 0.9 to 1.14.
Homologues: Orthologues: chimpanzee GPR12 (100% identical), macaque GPR12 (99% identical), dog GPR12 (97% identical), pig GPR12 (96% identical), mouse Gpr12 (94% identical), rabbit GPR12 (94% identical), rat Gpr12 (92% identical), tropical clawed frog gpr12 (86% identical), zebrafish gpr12 (74% identical). Paralogues in human: GPR6 (57% identical), GPR3 (56% identical), S1PR5 (28% identical), S1PR1 (27% identical), MC1R (26% identical), LPAR2 (25% identical), S1PR3 (25% identical), CNR1 (25% identical), LPAR1 (25% identical), CNR2 (25% identical), MC3R (25% identical), MC5R (25% identical), and 6 more.
Diseases named in the same sentence as GPR12 in open-access papers:
GPR12 is named in the same sentence as 24 diseases in open-access papers, as found by Europe PMC text mining. Sharing a sentence is not in itself a finding about the gene and the disease. The quoted sentences say what the papers report.
esophageal cancer (3 papers, 2022 to 2023). A primary or metastatic malignant neoplasm involving the esophagus. "Reversely, GPR12 was restrained in the esophageal cancer (EC) and hypopharyngeal cancer (HC) tissues; restored expression of GPR12 in EC and HC promoted tumor cell apoptosis by activating caspase-7." (PMID 37789353, 2023). "A recent study showed that GPR12 induces apoptosis by activating caspase-7, and inhibits the migration of hypopharyngeal, laryngeal, and esophageal cancer cells by promoting the expression of EMT-related proteins in hypopharyngeal, laryngeal, and esophageal cancer cells." (PMID 35155235, 2022).
hypopharyngeal cancer (3 papers, 2022 to 2025). Carcinoma, predominantly squamous cell, arising from the epithelial cells of the hypopharynx. "Zhang reported that GPR12 suppresses esophageal migration and promotes apoptosis in cancer and hypopharyngeal cancer." (PMID 40564276, 2025).
Obesity (3 papers, 2012 to 2022). Accumulation of substantial excess body fat. "In a previous study, we established a role of GPR12 in energy balance, as Gpr12 gene deficiency resulted in increased weight gain, decreased energy expenditure and dyslipidemia, with Gpr12 mutant mice showing symptoms of obesity." (PMID 22879962, 2012). "In our previous study, we could show that a Gpr12 deficiency resulted in dyslipidemia and signs of obesity as a result of changed energy homeostasis." (PMID 22879962, 2012). "In contrast, neural alterations derived from the absence of GPR12 in mice resulted in a phenotype of obesity and dyslipidemia, which suggests a possible role of this receptor in energy expenditure and energy homeostasis." (PMID 32457622, 2020).
Alzheimer disease (2 papers, 2024). A progressive, neurodegenerative disease characterized by loss of function and death of nerve cells in several areas of the brain leading to loss of cognitive function such as memory and language. "GPR3, GPR6, and GPR12 are expressed in various areas of the brain and peripheral tissues, where they play important roles in pathological conditions such as Alzheimer’s disease, Parkinson’s disease, addiction, obesity, and cancer." (PMID 39404382, 2024). "S1P, as an agonist on GPR3, GPR6, GPR12, may be a promising target in Alzheimer’s Disease." (PMID 38895631, 2024). "The discovery that GPR3, GPR6, and GPR12 are molecular targets for CBD provided important mechanistic insight for understanding the therapeutic potential of CBD for various diseases, including Alzheimer’s disease and Parkinson’s disease." (PMID 39404382, 2024).
Anxiety (1 paper, 2012). Intense feelings of nervousness, tension, or panic often arise in response to interpersonal stresses. "Therefore, by conducting a series of behavioural tests specifically designed to examine anxiety-related and depression-like behaviour as well as locomotion, it was deemed to be possible to infer the role of a Gpr12 gene dysregulation in Gpr12 mutant mice." (PMID 22879962, 2012).
Epithelial Ovarian Cancer (1 paper, 2022). "Interestingly, the mRNA expression of GPR12 is enhanced in ovarian cancer tissues relative to normal tissues, which is consistent with IHC results that GPR12 was upregulated in human EOC tissues." (PMID 35903681, 2022). "We further performed correlation analysis of GPR12 mRNA level with ERK1/2 cascade expression including MAP3K1, MAP2K1, MAP2K2, and MAPK1 by using ovarian cancer data from TCGA database." (PMID 35903681, 2022).
glioblastoma (1 paper, 2022). The most malignant astrocytic tumor (WHO grade IV). "Here, we found that GPR12 mRNA expression is extremely low in the majority of cancer types and significantly decreased in glioblastoma multiforme (GBM), brain lower grade glioma (LGG), and skin cutaneous melanoma (SKCM) tissues than matched normal tissues through pan-cancer analysis of GEPIA." (PMID 35903681, 2022).
metastatic cancer (1 paper, 2025). A carcinoma which has spread from the original site of growth to another anatomic site. "Brown reported that GPR12 may be involved in physiological processes such as the maintenance of oocyte meiotic arrest and brain development, as well as pathological conditions such as metastatic cancer." (PMID 40564276, 2025).
pancreatic adenocarcinoma (1 paper, 2022). "Meanwhile, in addition to EOC, results showed that a significant reduction in disease free survival only in patients with pancreatic adenocarcinoma (PAAD) with low GPR12 mRNA expression than those with high GPR12 mRNA expression." (PMID 35903681, 2022).
schizophrenia (1 paper, 2025). A major psychotic disorder characterized by abnormalities in the perception or expression of reality. "A future research direction to experimentally validate this association may highlight PUFA supplementation as a potential treatment for GPR12-related diseases, such as schizophrenia." (PMID 40405463, 2025).
cancer (4 papers, 2021 to 2025). A tumor composed of atypical neoplastic, often pleomorphic cells that invade other tissues. "GPR12 has been reported to be relevant to cancer metastasis via modulating the viscoelasticity of metastatic cancer cells by influencing phosphorylation and reorganization of keratin 8 filaments." (PMID 35903681, 2022). "Overexpression of GPR12 induced keratin 8 phosphorylation and reorganization, which might contribute to cancer cell metastasis." (PMID 37789353, 2023). "Similarly, G protein-coupled receptor 12 (GPR12) which is upregulated in the primitive subtype, is known to play a role in stem cell maintenance and somatic reprogramming of cancer stem cells." (PMID 33594052, 2021). "Based on the literatures included in PubMed, GPR12, ITM2B, ZNF24, and NSL1 were selected as the candidate targets due to the low expressions in various cancers." (PMID 37789353, 2023).
metabolic disorders (2 papers, 2012 to 2022). "Considering its unique distribution in the brain and its involvement in neuronal differentiation, further studies accounting for the genetic backgrounds should address potential compensatory effects and the further potential of GPR12 as a drug target for psychopathology and metabolic disorders." (PMID 22879962, 2012).
tumor (2 papers, 2022 to 2023). "Collectively, GPR12 might serve as a tumor suppressor in BC, but the exploration of detailed mechanism was in need." (PMID 37789353, 2023). "Reversely, the anti-tumor function of miR-105-5p antagomir was observed in the xenograft mice.CSCs aggravated the malignancy of BC partly through transmitting exosomal miR-105-5p to BC cells to inhibit the expression of GPR12, which developed a novel aspect for CSC-targeted therapies." (PMID 37789353, 2023). "In addition, Hematoxylin-Eosin (HE) staining and TdT-mediated dUTP-biotin nick end labeling (TUNEL) staining showed that GPR12 knockdown significantly increased the tumor necrotic area and the number of apoptotic cells in the tumor tissues of mice compared with scramble group, respectively." (PMID 35903681, 2022). "Analysis of tumor lysates from scramble and GPR12 knockdown mice showed a significant decrease in phosphorylated ERK1/2 protein levels in GPR12 knockdown tumors." (PMID 35903681, 2022). "In the present study, we characterized the expression of GPR12 and its clinical and prognostic relevance in EOC and found that GPR12 may function as a tumor promotor in EOC." (PMID 35903681, 2022).
neurodegenerative disease (1 paper, 2024). A disorder of the central nervous system characterized by gradual and progressive loss of neural tissue and neurologic function. "Molecules targeting GPR3, GPR6 and GPR12 are of interest for therapeutic applications since they are implicated in several neurodegenerative diseases, including AD, PD, HD and MS." (PMID 38895631, 2024). "Despite the promising roles of GPR3, GPR6, and GPR12 in neurodegenerative diseases, including AD, further research is required to fully elucidate their mechanisms of action and validate them as viable therapeutic targets." (PMID 38895631, 2024).
GPR12 also shares sentences with these, for which no sentence is quoted: dyslipidemia (2 papers); bladder cancer (1); clear cell adenocarcinoma (1); depression (1); endometrioid adenocarcinoma (1); mucinous adenocarcinoma (1); ovarian cancer (1); Parkinson disease (1); serous ovarian cancer (1); skin cutaneous melanoma (1).